ANXA1 (annexin A1)
Diseases named in the same sentence as ANXA1 in open-access papers (continued):
Sharing a sentence is not in itself a finding about the gene and the disease.
infection (continued). "Conversely, AnxA1 levels were increased both in the gut and systemically during the chronic phase of infection in the animals." (PMID 37190040, 2023). "As seen for BALB/c and C57BL/6 strains, DENV-infected A129 mice showed reduced AnxA1 plasma levels over the course of infection, compared with mock-infected animals." (PMID 35293862, 2022). "Here, we show that glycoprotein E (gE) binds to the cellular protein, annexin A1 (Anx-A1) to enhance infection." (PMID 35939498, 2022). "During infection, AnxA1 KO mice presented an increase in the histopathological score with exacerbation of inflammatory infiltrate and damage to muscle architecture." (PMID 36078125, 2022). "Of note, whilst increased haematocrit levels and vascular leakage were observed as early as 24-hr post-infection in vehicle-treated mice, treatment with AnxA1 mimetic peptide delayed the onset of both disease manifestations." (PMID 35293862, 2022). "ELISA confirmed that the increased cytokine production (CXCL1, CXCL2, IL-6, and IL-1β) induced by bacterial infection was reverted by AnxA1 treatment in WT mice at 14 h after infection." (PMID 33318141, 2021). "Histopathological analysis of brain tissues from WT and Fpr2−/− mice revealed that AnxA1 administration prevented infection-induced brain damage in WT mice." (PMID 33318141, 2021). "Before S. suis (1.25 × 105 CFU) infection, a prophylactic dose of AnxA1 (25 or 50 μg/kg of body weight) was given to WT and Fpr2−/− mice via the intravenous (i.v.)route, after which neutrophil counts and MPO levels were measured." (PMID 33318141, 2021). "The presence of ANXA1 promotes viral entry by influencing viral binding to target cells, enhances viral replication upon infection and promotes the trafficking of the virus to the nucleus." (PMID 32541772, 2020). "Plaque assays revealed significantly lower virus levels in AnxA1-treated mice, suggesting that AnxA1 treatment prior to infection counteracted viral propagation." (PMID 31398292, 2019). "Infection with IAV enhanced ANXA1 expression, and overexpression of ANXA1 in A549 lung epithelial cells enhanced virus replication in vitro." (PMID 30498445, 2018). "In accord with these data, a recent report showed that Annexin A1-deficient mice are protected from IAV replication and virus-induced lethal infections." (PMID 28928730, 2017). "Another possibility is that the initial protective host response to infection required to eliminate the virus is impaired because FPR2 is inadequately activated after infection by IAV-expressing Annexin A1." (PMID 28928730, 2017). "In the early infection and during transition from acute to chronic stage of infection (2–10wks), the ANXA1 expression was up regulated in peripheral blood of SIV-infected animals." (PMID 27484833, 2016). "ANXA1 gene expression was analyzed in both peripheral blood and gut mucosal compartments at pre-infection time point and at 2, 10 and 26 weeks following SIV infection." (PMID 27484833, 2016). "In fact, plasma viral load and CD4+ T cell counts declined throughout the infection, accompanied with increased ANXA1 expression in PBMCs and in the gut." (PMID 27484833, 2016). "Female mdx myotubes showed a significantly lower level of cell death (29.9±4.2%) in mdx myotubes infected with retroviral annexin A1 expression vector after hypo-osmotic shock, compared to the control empty vector infection group (53.2±7.3%)." (PMID 25775477, 2015). "We investigated the distribution of annexin A1 and A2 protein within the respiratory tract of healthy cattle, and compared this to the levels found after experimental infection with M. haemolytica." (PMID 25827591, 2015). "In our study, several proteins involved in inflammation and infection processes, such as Annexin A1, Complement component 1 Q subcomponent-binding protein (C1qBP), Poly(rC)-binding protein 2 (hnRNP E2) are indentified." (PMID 24454774, 2014).
infection (continued). "At 60 and 120 min after initial infection with T. gondii, an intense immunoreactivity of ANXA1 was detected in the nucleus and cytoplasm of infected cells compared to control cells." (PMID 22740770, 2012). "Densitometric analysis confirmed our histological data, which exhibited a significant increase in the expression of ANXA1 in the neutrophils of T. gondii-infected eyes at 24, 48, and 72 h after initial infection as compared to the respective control groups." (PMID 22740770, 2012). "Densitometric analysis revealed that T. gondii infection significantly augmented ANXA1 protein levels at 60 and 120 min after infection, followed by a decrease at 240 min and 24 h after infection." (PMID 22740770, 2012). "At 24, 48, and 72 h after intravitreal tachyzoite infection, a significant increase in ANXA1 levels in the neutrophils of the anterior and posterior eye segment was detected compared to control cells." (PMID 22740770, 2012). "Despite lower mRNA for NR3C1 during infection (-1.33-fold), we observed up-regulation of ANXA1 (1.38-fold change)." (PMID 19925655, 2009). "This suggests a differential effect of ANXA1 on inflammation induced by lipopolysaccharide and infection with S. Typhimurium." (PMID 19049646, 2008). "Infection of wild-type and ANXA1 knock-out mice with S. Typhimurium led to similar organ bacterial loads." (PMID 19049646, 2008). "Loss of ANXA1 does not alter infection by the non-astrovirus panel tested, indicating selectivity for PAstV under our conditions." (PMID 41628256, 2026). "Given the observed increase in AnxA1 in the lungs of MHV-3 infected mice and its known role in containing exacerbated inflammation in different contexts, we evaluated the possible contribution of this protein during MHV-3 infection in AnxA1 genetic ablated mice (AnxA1KO) (scheme inFigure 2A)." (PMID 40956847, 2025). "Altogether, these studies indicate that infection with HPV enhances AnxA1 expression and this protein may play a role in HPV-mediated carcinogenesis." (PMID 37190040, 2023). "Collectively, these studies suggest that the AnxA1/FPR2 axis could be a potential target for host-directed therapies for arbovirus-induced infections, such as CHIKV, DENV, and ZIKV, due to its protective role in these diseases." (PMID 37190040, 2023). "Interestingly, a study by Schloer and co-workers showed that the treatment with human recombinant AnxA1, four days prior to infection of mice, expands the population of alveolar macrophages (AMs) and provides protection against infection." (PMID 37190040, 2023). "Reduced expression of placental AnxA1 was observed in mothers post ZIKA infection." (PMID 37373303, 2023). "However, Arora and colleagues have demonstrated in a murine model of influenza A that AnxA1 KO mice showed an increased viral clearance and accumulation of neutrophils at the infection site." (PMID 36078125, 2022). "Histopathological analysis at 1, 7, or 14 days post-infection revealed a significant increase in tissue injury and showed that paws of AnxA1 KO mice had greater tissue inflammation compared with WT (BALB/c) mice, peaking at 7 dpi, indicating a protective role of AnxA1 in CHIKV disease." (PMID 36078125, 2022). "The AnxA1 peptide was effective even when administered from day 2 after the infection onset." (PMID 35293862, 2022). "Given the debate regarding the factors that affect HAM/TSP pathogenesis, in the present study, we investigated the potential association of AS HTLV-1 infection or infection with HAM/TSP symptoms and the gene expression of ANXA1 and its receptors (FPRs) in peripheral blood cells." (PMID 33632146, 2021). "Thus, the bacterial loads in the blood and brain homogenate of infected mice treated with 50 μg/kg AnxA1 or vehicle were assessed at 14 h after infection." (PMID 33318141, 2021). "In addition to the association between ANXA1 mRNA transcription and HTLV-1 infection, a relationship was observed between infection and FPR mRNA levels." (PMID 33632146, 2021).
infection (continued). "Furthermore, expression levels of ANXA1 were increased in porcine monocytes during infection with swine flu virus, and in human nasal swabs of influenza A virus-infected patients." (PMID 32512864, 2020). "However, because we found a beneficial effect of the AnxA1 treatment to reduce virus titers at very early stages of the infection, it is highly likely that increased uptake of the incoming viral particles by activated AMs limits the infection." (PMID 31398292, 2019). "Similarly, BAL fluids revealed a trend toward lower cytokine levels in AnxA1-treated mice infection." (PMID 31398292, 2019). "ANXA1 expression was suppressed in the gut but systemically increased during early infection." (PMID 27484833, 2016). "This is the first time a paper analyses the expression of ANXA1 in infection by this parasite." (PMID 24359168, 2013). "At 240 min and 24 h after infection, a low level of ANXA1 expression was noted in these cells." (PMID 22740770, 2012). "Notably, infection is reduced but not abolished in ANXA1-deficient cells, consistent with additional entry factors acting alongside ANXA1." (PMID 41628256, 2026). "In addition, the following were observed in cats after infection with T. gondii: malate dehydrogenase, serotransferrin, keratin, phosphoglycerate mutase, elongation factor, ceruloplasmin, gelsolin, crystalline alpha chain and annexin A1." (PMID 34906132, 2021). "Notably, primary cells derived from lungs of control and AnxA1-treated mice were equally susceptible to infection by IAV, indicating that the treatment did not induce an IFN-induced antiviral state." (PMID 31398292, 2019). "Importantly, the data suggests that ubiquitin, annexin A1, annexin A2, MavP are putative novel interaction partners and that Rab1A, Rab1B, Rab6, and Rab10 are the predominant Rab GTPases targeted by SidM during infection." (PMID 26755725, 2016). "Our data showed divergent ANXA1 gene expression patterns in peripheral blood and gut mucosa in vivo during primary acute and chronic stages of viral infection, which may be associated with chronic SIV-infection induced immune activation." (PMID 27484833, 2016). "The effect of ANXA1 on the host response to infection is unknown." (PMID 19049646, 2008). "The role of ANXA1 in modifying the host response to lipopolysaccharides suggests that this protein might either decrease the inflammatory response of the host to S. Typhimurium infection or modulate some of the effects of glucocorticoids during infection." (PMID 19049646, 2008). "It was reported that the binding of AnxA1 to glycoprotein E (gE) on the HSV-1 envelope enhances virus binding and facilitates the infection of A549 or N18 cells." (PMID 37190040, 2023). "In this study, LXA4 and AnxA1 were used as an intervention in STSLS infection to explore the potential effects of LXA4 and AnxA1 in STSLS treatment." (PMID 36776849, 2023). "Plasma levels of mast cell protease 1 (MCPT-1) and CCL2 were increased in either AnxA1 and FPR2 KO animals compared to their respective controls after infection." (PMID 35293862, 2022). "(B) WT BALB/c mice and AnxA1 KO mice or (C) WT C57BL/6 and FPR2 KO mice were pre-treated with Ac2-26 (i.p; 150 μg) 1 hr before infection with 1 × 106 PFU of DENV-2 via footpad injections (n = 5 for all groups, except for FPR2 KO mock, n = 4)." (PMID 35293862, 2022). "The expression of the anti-inflammatory molecules IL-10, ANXA1, DUSP1, GILZ and HO-1 was significantly increased upon infection." (PMID 34843584, 2021). "ANXA1 was found to enhance the expression of a cytoplasmic RNA sensor, RIG-I basally and post-infection." (PMID 32541772, 2020). "Next, to investigate the role of ANXA1 and RIG-I in IAV-induced cell death, A549, A549∆ANXA1, and A549 ∆RIG-I cells were infected with 1 multiplicity of infection (MOI, i.e., 1 viral particle per cell) H1N1 PR8 virus for 24 and 48 h." (PMID 32541772, 2020).
infection (continued). "At early stages of infection, the percentage of AMs in the BAL fluid of AnxA1-treated mice compared with control mice was still significantly elevated." (PMID 31398292, 2019). "Lenti-miRZip-128a infection decreased the levels of mature miR-128a and significantly enhanced the expression of Lin28A, EGR2, ZFP36 and ANXA1." (PMID 28569789, 2017). "During early infection (2wk), expression of pro-inflammatory cytokines IFN-γ, TNF-α, IL-17, IL-18, IL-22 (Th1 and Th17 responses) was negatively correlated with ANXA1 expression." (PMID 27484833, 2016). "In vitro studies confirmed an upregulation of ANXA1 levels in RPE cells, after 60 and 120 min of infection with T. gondii." (PMID 22740770, 2012). "Our ultrastructural immunocytochemistry data revealed an overexpression of the anti-inflammatory ANXA1 protein in RPE cells after 48 and 72 h infection by T. gondii." (PMID 22740770, 2012). "Additionally, some viruses can hijack the binding of AnxA1 to the FPR2 receptor, and enhance the infection of the cells." (PMID 37190040, 2023). "Conversely, treatment of wild-type animals with the AnxA1 mimetic peptide (Ac2–26) reduced neutrophil accumulation, decreased local concentration of inflammatory mediators and diminished mechanical hypernociception and paw edema induced by CHIKV-infection." (PMID 36078125, 2022). "Next, to investigate if ANXA1 plays a role in the intracellular degradation process induced by IAV infection, both A549 cells and A549-ΔANXA1 cells were infected with H1N1 PR8 IAV at multiplicity of infection (MOI) 1 over various time points." (PMID 32512864, 2020). "Consistent with a state change, all clones failed to rescue the sensitivity to DENV-luc infection and express Annexin A1 at levels similar to the knockout." (PMID 32463448, 2020). "Dexamethasone, therefore, had similar effects on S. Typhimurium infection in both ANXA1+/+ and ANXA1−/− mice, suggesting that ANXA1 is unlikely to be important in mediating the effects of glucocorticoids during the early phase of this infection." (PMID 19049646, 2008). "As a non-specific metalloprotease, GP63 may cleave mammalian ANXA1, thereby enabling its interaction with the FPRs on monocytes, enhancing their recruitment and infection by the parasite." (PMID 39076982, 2024). "Collectively, these observations indicate that the ANXA1-dependent effect of leishmanial exosomes does not significantly influence the generation of a protective adaptive immune response at later time points post-infection." (PMID 39076982, 2024). "Overall, the AnxA1 pathway appears to be beneficial for controlling excessive inflammation and hypernocyception in arboviral diseases, without affecting the ability of the host to fight infection." (PMID 37190040, 2023). "Indeed, low levels of AnxA1 in the peripheral blood of HTLV-1 patients were observed, which may be related to an anti-inflammatory effect during infection." (PMID 37190040, 2023). "Furthermore, cells containing AnxA1 were observed throughout the epidermis, i.e., keratinocytes, and in the connective tissue cells, mainly infiltrated leukocytes, in WT (BALB/c) mice after infection with CHIKV." (PMID 36078125, 2022). "In contrast, a striking reduction of ANXA1 expression was seen in the gut mucosa at all time points during SIV infection (fold change average, FC = −4.5), indicating that SIV infection led to differential systemic and mucosal modulation of ANXA1 expression during early stages of infection." (PMID 27484833, 2016). "Our data suggest that ANXA1 plays no role in the pathogenesis of infection and it may be that peptides based on ANAX1 could therefore be useful immunomodulators in infected patients." (PMID 19049646, 2008). "The effects of glucocorticoids are independent of ANXA1, suggesting that while this protein modulates some of the effects of exogenously administered lipopolysaccharide, it does not affect the host response to infection with S. Typhimurium." (PMID 19049646, 2008).
infection (continued). "Notably, several members from Annexin A family (ANXA1, ANXA2, ANXA4, ANXA5 and ANXA6) were overrepresented in DEVs from Lm-infected BMDCs but remained unaltered in total cell lysates, suggesting a specific sorting during infection of these ANXA family members to EVs." (PMID 36131943, 2022).
cardiovascular disease (12 papers, 2014 to 2025). "Additionally, annexins included in the pathways upregulated in iVSMCs have been linked to cardiovascular disease and identified as having therapeutic potential (ANXA1, ANXA2)." (PMID 39796045, 2024). "Future research should focus on validating ANXA1 as a therapeutic target through large‐scale clinical trials and exploring its role in other cardiovascular diseases." (PMID 41208642, 2025). "Considering the protective effect of ANXA1 in circulatory system diseases, the main studies on ANXA1 in the occurrence and development of CD are summarized below." (PMID 41208642, 2025). "Despite this evidence for the relationship of mutual regulation between ABCA1 expression and ANXA1 efflux, less is known regarding the potential role of this mutual regulatory effect in cardiovascular disease." (PMID 32894039, 2020). "ANXA1 small peptide (ANXA1sp), a bioactive peptide derived from ANXA1, exhibits biological effects similar to those of ANXA1, hinting that ANXA1sp also plays a cardioprotective role in cardiovascular diseases." (PMID 37057132, 2023). "Role of and therapeutic potential of Annexin A1 in cardiovascular disorders." (PMID 34943928, 2021). "Thus, studies focused on long-term outcomes of Annexin A1 modulation in cardiovascular disorders is necessary to better establish its therapeutic potential." (PMID 34943928, 2021). "With respect to the receptor target for AnxA1, the formyl peptide receptor 2 or FPR2,130 a single nucleotide mutation (A>G) in the core promoter has been identified in one individual with history of cardiovascular disease, a gene defect passed to his offspring." (PMID 41205263, 2025). "Moreover, ANXA1 also plays an advantageous role in cardiovascular diseases." (PMID 37057132, 2023).
larynx (8 papers, 2014 to 2025). "IHC confirmed the reduced expression of ANXA1 in the nucleus and cytoplasm of larynx tumors compared to normal tissue, while an increase in ANXA1 expression was detected in the membrane of tumorous versus normal tissue." (PMID 38893148, 2024). "In conclusion, our high‐throughput data analysis revealed that the enhanced interaction between monocytes and liver sinusoidal endothelial cells, along with the upregulated expression of ANXA1/FPR2, are among the distinguishing features before and after liver IR injury." (PMID 39993960, 2025).
metabolic disease (7 papers, 2019 to 2024). A congenital disorder (due to inherited enzyme abnormality) or acquired (due to failure of a metabolically important organ) disorder resulting from an abnormal metabolic process. "These investigations have emphasized the potential of ANXA1 to exert protective actions in the context of neuroinflammatory, neurovascular, and metabolic diseases." (PMID 38961424, 2024). "Much of what is known about the function of ANXA1/FPR2 in the context of metabolic disease is in the periphery." (PMID 37208759, 2023). "The opposing outcome of these two studies clearly illustrates that further research is needed to resolve the role of AnxA1 in adiposity and metabolic diseases." (PMID 31337068, 2019). "Recently, evidence has shown that ANXA1 could be used as a possible new therapeutic avenue via repairing blood-brain barrier damage in metabolic disease." (PMID 35664067, 2022). "Last, there is evidence that Annexin A1, an endogenous molecule endowed with resolving/protecting action on tight junctions, may have therapeutic potential in restoring cerebrovascular damage and BBB disruption in neurodegenerative diseases and metabolic disorders." (PMID 36591311, 2022).